CD1C (CD1c molecule)
Diseases named in the same sentence as CD1C in open-access papers (continued):
Sharing a sentence is not in itself a finding about the gene and the disease.
posterior non-infectious uveitis (1 paper, 2023). "RNA-seq analysis (RNA-seq) was performed on lineage (CD3−CD19−CD56−CD14−)-negative, and HLA-DR-positive, CD11c and CD1c-positive DCs purified from frozen PBMCs by flow cytometry from 36 patients with anterior (AU), intermediate (IU), or posterior non-infectious uveitis (BU) and healthy controls." (PMID 37042831, 2023).
preeclampsia (1 paper, 2020). Preeclampsia is a hypertensive disorder of pregnancy that is characterized by new-onset hypertension with proteinuria presenting after 20 weeks of gestation, and depending on mild or severe forms may initially present with severe headache, visual disturbances, and hyperreflexia. "Compared with healthy pregnancy, the expression of B7-H4 on myeloid and plasmacytoid DCs is higher on CD1c+ myeloid DCs of patients with preeclampsia than on those of patients without preeclampsia." (PMID 32265918, 2020).
Q fever (1 paper, 2022). A bacterial infection caused by Coxiella burnetii. "Percentages of CD3+ T cells, CD20+ B cells, CD1c+ cDC2, CD15+ neutrophils, and CD68+ macrophages are similar between the groups with atherosclerotic AAA and Q fever AAA." (PMID 35137689, 2022).
reactive lymphoid hyperplasia (1 paper, 2023). "Among 19 cases of reactive lymphoid hyperplasia, 12 had low CD1c expression, and seven had high CD1c expression." (PMID 38099311, 2023).
sickle cell disease (1 paper, 2020). Sickle cell anemias are chronic hemolytic diseases that may induce three types of acute accidents: severe anemia, severe bacterial infections, and ischemic vasoocclusive accidents (VOA) caused by sickle-shaped red blood cells obstructing small blood vessels and capillaries. "It remains to be determined whether these monocytes in the blood of sickle cell disease patients are akin to the CD14+ subset of CD1c+ DCs." (PMID 33101275, 2020). "An informative example is sickle cell disease, which goes along with increased blood GM-CSF levels, with increased numbers of CD16+ monocytes and with expression of CD1c on monocytes." (PMID 33101275, 2020).
squamous cell carcinoma (1 paper, 2011). A carcinoma arising from squamous epithelial cells. "This resultis different from the observations we made in other disease models, includingpsoriasis and squamous cell carcinoma, where the CD11c+ CD1c+ DCpopulation stays relatively unchanged in number, but the CD11c+ CD1c−DC population shows a dramatic expansion." (PMID 21541348, 2011).
Stroke (1 paper, 2021). Sudden impairment of blood flow to a part of the brain due to occlusion or rupture of an artery to the brain. "However, only cDC2s (human: CD1c+, mouse: CD172a+) have been detected in the brain using post‐mortem brain tissue and following experimental stroke." (PMID 33205448, 2021).
tonsillar cancer (1 paper, 2018). "In further support of an immunosuppressive profile, the IL-10 signaling pathway was an enrichment hit for CD1c+ mDCs in tonsillar cancer." (PMID 29795118, 2018). "This study identified selectively expressed surface markers on specific DC subsets in tonsillar cancer, and CD206/MRC1 and CD207/Langerin on CD1c+ mDCs were confirmed at protein level." (PMID 29795118, 2018). "We describe, for the first time, four subsets of DCs in tonsillar cancer: CD123+ plasmacytoid DCs (pDC), CD1c+, CD141+, and CD1c−CD141− myeloid DCs (mDC)." (PMID 29795118, 2018). "Accordingly, we describe, for the first time, CD123+ pDCs, CD1c+ mDCs, CD141+ mDCs, and DN mDCs in tonsillar cancer and compare their transcriptional profiles to each other and to their counterparts in benign tonsils." (PMID 29795118, 2018). "Levels of CD1c+ mDCs and CD141+ mDCs were similar between tonsillar cancer and benign tonsils." (PMID 29795118, 2018).
vitiligo (1 paper, 2011). Generalized well circumscribed patches of leukoderma that are generally distributed over symmetric body locations and is due to autoimmune destruction of melanocytes. "By immunohistochemistry staining, weobserved enhanced populations of CD11c+ myeloid dermal DCs andCD207+ Langerhans cells in leading edge vitiligo biopsies.DC-LAMP+ and CD1c+ sub-populations of dermal DCs expandedsignificantly in leading edge and lesional vitiligo skin." (PMID 21541348, 2011). "Here, the CD11c+ CD1c+ dendriticcells were found throughout the upper dermis of non-lesional, lesional andleading edge vitiligo skin." (PMID 21541348, 2011).
tumor (125 papers, 2012 to 2025). "In lung adenocarcinomas with EGFR mutations, CD1C+ dendritic cells are increased, and tumor‐associated macrophages display tumor‐promoting functions with significant heterogeneity." (PMID 40062730, 2025). "In this study, we demonstrate that CD14− cDC2s can directly convert to CD1c+CD14+CD163+ DCs driven by tumor-associated factors." (PMID 38242119, 2024). "CIBERSORT showed that CD1C levels were associated with tumor immune infiltrating cells (TILs), such as different kinds of T cells." (PMID 36755259, 2023). "Further enrichment analysis of GSEA and GSVA showed that CD1C plays a role in a variety of immune associated pathways.The CIBERSORT algorithm was used to calculate tumor immune infiltrating cell (TIL) subsets in the TME of BRCA." (PMID 36755259, 2023). "Auto reactivity was also observed in CD1c-restricted T cells and they have been specifically linked to tumour-derived lipid-antigens." (PMID 37256718, 2023). "We found that both mRNA and protein expression of Cd1c were down-regulated in LUAD tumor tissues, while the down-regulation of Cd1c was associated with poor survival." (PMID 34805160, 2021). "Within tumors, accompanied by an increase in CD1C+ dendritic cells, the tumor-associated macrophages (TAMs) showed pro-tumoral functions without signature gene expression of defined M1 or M2 polarization." (PMID 33144684, 2021). "The released tumor-associated antigens and damage-associated molecular pattens will favor antigen uptake and the maturation of intratumoral co-administered CD1c (BDCA-1)+ myDCs." (PMID 33182610, 2020). "We identified six clusters which displayed expression of markers previously reported to be associated with multiple myeloid subpopulations including classical tumor-infiltrating monocytes, inflammatory and regulatory tumor-associated macrophages, and conventional CD1c+ dendritic cells." (PMID 39424708, 2025). "The association between CD1C levels and tumor stage was assessed." (PMID 36755259, 2023). "Our data may be helpful in revealing new cellular mechanisms related to the induction of tolerogenic CD1c+ DCs by NSCLCs and the development of an immune suppressive microenvironment that causes tumor cells to escape immune surveillance." (PMID 31921114, 2019). "Additionally, high CD1c expression in dendritic cells may be closely associated with their immunological function in the immune system and play an essential role in tumor treatment." (PMID 38099311, 2023). "However, this approach should be carefully evaluated because it may associate with unwanted potential on-target/off-tumor elimination of the endogenous CD1c+ APCs presenting mLPA to engineered T cells." (PMID 34381053, 2021). "In particular, cDCs, including the BDCA-3 (CD141)+ cDC1 and BDCA-1 (CD1c)+ cDC2 subsets, are key to tumor antigen cross-presentation." (PMID 40955425, 2025). "CD1C+ dendritic cells are thought to induce the CD4+ helper T cell response for tumor antigen presentation." (PMID 41279473, 2025). "Before the classification of DC3s, CD1c+CD14+ DCs were reported in various tumor contexts, also often referred as inflammatory DCs." (PMID 40584260, 2025). "The analysis revealed a strong distribution preference of F13A1+ Mφ and CD1C+ cDC2 in tumours from MPLCs, as compared to tumours from SPLCs and normal tissues from both MPLCs and SPLCs." (PMID 39601163, 2024). "Increased frequencies of DC3s (CD1c+CD14+) are reported in tumor context but a detailed investigation into their development, characteristics, and plasticity is lacking." (PMID 38242119, 2024). "In a tumor context, another layer of complexity is added to the origin and development of CD1c+CD14+ DCs." (PMID 38242119, 2024). "Monoculture in tumor-conditioned medium (CM) caused a similar increase in the amount of CD1c+CD14+ cells (63% and 54%) as direct tumor-cell contact, whereas cDC2s cultured in medium led to 16% CD14+ cells." (PMID 38242119, 2024).
tumor (continued). "CD1c(BDCA-1)+/CD141(BDCA-3)+ myeloid dendritic cells (myDC) in the tumor microenvironment are indispensable at initiating effector T-cell responses and response to ICB." (PMID 38954010, 2024). "After having observed the influence of the tumor on CD1c+CD14+ cell frequencies, we continued with investigating potential precursors of tumor-induced CD1c+CD14+ cells." (PMID 38242119, 2024). "Myeloid dendritic cells—in particular CD1c(BDCA-1)—play a pivotal role in favorable and “hot” tumor microenvironments." (PMID 39682081, 2024). "In this phase II clinical trial, anti-PD-1 ICB pretreated oligometastatic patients (tumor agnostic) underwent a leukapheresis followed by isolation of CD1c(BDCA-1)+/CD141(BDCA-3)+ myDC." (PMID 38954010, 2024). "Cell communication analysis also revealed specific interactions between CD1C+ cDC2 cells and T/NK cells in multi‐primary tumours, highlighting the involvement of CLEC2B/CLEC2C molecules and KLRB1 as ligands in this interaction." (PMID 39601163, 2024). "The increased frequencies and low immunostimulatory capacity of CD1c+CD14+ cells urged us to study their development in tumor context." (PMID 38242119, 2024). "The consistent up‐regulation of F13A1 and CD1C across multiple nodules in different patients underscores their significance in the context of multiple primary tumours." (PMID 39601163, 2024). "Active treatment consisted of intranodally injected autologous CD1c+ conventional and plasmacytoid DCs loaded with tumor antigens." (PMID 38395969, 2024). "TIMELESS expression was significantly negatively correlated with neutrophil biomarkers (CEACAM8) and dendritic cell biomarkers (HLA-DPB1, HLA-DQB1, HLA-DRA, HLA-DPA1, CD1C) in TCGA LUAD tumor tissues." (PMID 38261568, 2024). "Higher frequencies of tumor-infiltrating CD1c+ DCs coincided with significantly lower survival rates (19.2 ± 17.2 vs. 42.9 ± 15.9 months for low frequencies)." (PMID 38242119, 2024). "Based on the experimental results and previous related literature, the possible mechanism and biological function of CD1c in tumor prognosis were explored." (PMID 38099311, 2023). "We performed immunohistochemical staining of CD4, CD8, CCL19, Ki-67, and CD1C in serial sections of the same tumor tissue of BRCA patients." (PMID 36755259, 2023). "Bioinformatic analysis shows CD1c is involved in tumor-related signaling pathways and immune and metabolic processes." (PMID 38099311, 2023). "We found a significant difference in the expression level of CD1c between normal and tumor tissue (P < 0.05)." (PMID 38099311, 2023). "In the 105 BRCA patients from The Second Affiliated Hospital of Anhui Medical University, we compared differential expressions of CD1C in different subgroups based on grade, tumor stage, and molecular typing by IHC." (PMID 36755259, 2023). "The present statistical analysis revealed that CD1C expression in BRCA was negatively associated with grade, tumor stage, and T classification." (PMID 36755259, 2023). "In further paired analysis, CD1C levels in tumor samples were markedly lower than in normal samples." (PMID 36755259, 2023). "The expression of CD1c mRNA and protein levels was verified by wet experiments at cell and tissue levels, indicating that CD1c was more expressed in tumor tissues than in reactive hyperplasia tissues, and the high expression group had a poor prognosis." (PMID 38099311, 2023). "Significant statistical differences were found in the mRNA expression of CD1C in tumor tissues and adjacent tissues." (PMID 36755259, 2023). "CD1C+ DCs were found to initiate tumor specific immune reactions when cultured in vitro and injected into patients." (PMID 36755259, 2023). "Conversely, CD1C+ DCs were enriched in tumor tissues and expressed higher levels of CCL17 and CCL22, which can recruit Tregs to induce immunosuppression in the TME." (PMID 37187731, 2023).
tumor (continued). "Western blotting results showed that the expression of CD1C protein in tumor tissues was significantly lower than that in adjacent tissues." (PMID 36755259, 2023). "CD1c mRNA levels were compared between normal tissues downloaded by GETx and tumor tissues of TCGA-DLBC." (PMID 38099311, 2023). "Our previous study verified that compared with their corresponding tumor-free liver tissues (TFLs), the percentage of infiltrating CD1c+ myeloid DCs (mDCs) was significantly decreased in liver tumor tissues." (PMID 35321724, 2022). "A similar tendency was also observed for the CD1c+ population of tumor border (HR-positive BC: 24.13 ± 23.79, HR-negative BC: 4.25 ± 7.98, p = 0.057)." (PMID 35955602, 2022). "It almost had no expression in the normal sample but was obviously expressed in tumor samples, specially expressed in natural killer cell_2 and CD1C+_B dendritic cell_3." (PMID 35769782, 2022). "Macrophages and CD1a + DCs (DC_c3_CD1A) were significantly enriched in tumors compared with paired non-tumor tissues, while monocytes, CD1c+ DCs (DC_c1_CD1C), and cDC1 DCs (DC_c2_XCR1) showed the opposite trend." (PMID 35347134, 2022). "We also found that several genes, including TYROBP, CD1C, KIR2DL3, CD3G, and TARP, were significantly highly expressed in patients with a high tumor mutational burden." (PMID 35204406, 2022). "Similar observations were made for DC-LAMP+ and CD1c+ cells at tumor border (R = 0.47, p < 0.001) as well as in the distant area (R = 0.27, p < 0.006)." (PMID 35955602, 2022). "The densities of DC-SIGN+ cells at tumor border correlated with DC-LAMP+ cells (R = 0.41, p < 0.004) and CD1c+ cells (R = 0.41, p < 0.005) at the tumor edge as well as with intratumoral CD1c+ population (R = 0.33, p < 0.035)." (PMID 35955602, 2022). "Despite a wide array of evidence supporting a predominant role of cDC1s in anti-tumor immunity, CD1c+ CD14− cDC2s also participate by infiltrating tumors and triggering CD4+ T cell responses at tumor draining lymph nodes." (PMID 36230990, 2022). "Four cell types, SELENOP+M4, CXCL9+M2, CD1C+DC1, and CLEC9A+DC2, were negatively associated with tumor progression (FDR < 0.05)." (PMID 34659209, 2021). "Messenger RNA expression of CD1C and CD1E, a TCR contributory gene, was associated with T regulatory (Treg) cell infiltration (r > 0.35) and M2 macrophage (r > 0.43) tumour infiltration." (PMID 34664400, 2021). "Among the four clusters of dendritic cells, DC_C2_CD1C, DC_C3_LAMP3, and DC_C4_JCHAIN were derived from tumours, and DC_C1_FCER1A was derived from peripheral blood, which was assigned as monocyte-like DC because of the expression of monocyte marker S100A8." (PMID 33531485, 2021). "In order to increase the amount of available tumor antigen and optimize the maturation potential of CD1c (BDCA-1)+ myDCs in situ, the IgG1 subtype monoclonal antibodies ipilimumab and avelumab were co-injected in order to induce ADCC and CDC." (PMID 33182610, 2020). "All DC subsets phagocytosed necrotic tumor cells, but CD1c+ DCs and monocytes were much more effective." (PMID 32655564, 2020). "Intracellular accumulation of mLPA in tumor cells is thought to increase CD1c-restricted presentation of mLPA on the cell surface compared to normal cells, and therefore leading to differential recognition of malignant cells with mLPA-restricted T cell clones." (PMID 33262761, 2020). "A previous study showed that mice containing autoreactive CD1c-restricted T cells were efficient in eliminating human leukemic cells, suggesting that these autoreactive CD1c-restricted T cells play a role in tumor immunity." (PMID 31013709, 2019). "H-1299 tumor cells modulate the production of pro- and anti-inflammatory cytokines in CD1c+ DCs isolated from NSCLC patients." (PMID 31921114, 2019). "Our data indicated that co-culture with H-1299 tumor cells modulates the development of CD1c+ DC subpopulations, which is mediated by CD205 and CD103, derived from healthy donors." (PMID 31921114, 2019).